G0S2 (G0/G1 switch 2)
Diseases named in the same sentence as G0S2 in open-access papers (continued):
Sharing a sentence is not in itself a finding about the gene and the disease.
tumor (continued). "We therefore combined methylation data from patient tumor tissues and cell lines following decitabine treatment to converge on six genes (CRIP1, G0S2, MLH1, OPN3, S100 and TUBB2A) as the classifier." (PMID 25391133, 2014). "In the context of tumor biology, the mechanisms by which G0S2 operates are not yet fully understood." (PMID 40282408, 2025). "Further, the combination of G0S2 inhibitor (NS-3-008) and anti-PD-1 antibody treatment significantly suppressed tumor volume and promoting CD8+ T cells function.These findings suggest that G0S2 may serve as a metabolic target that influences immune responses." (PMID 40519301, 2025). "G0S2 knockout activated the type I interferon signaling pathway, enhanced CD8+ T cell functionality, and synergized with anti-PD-1 therapy, resulting in suppressed tumor growth and prolonged survival in vivo." (PMID 40519301, 2025). "Then, we found that G0S2 and PDCD4 were downregulated in the tumor tissue by performing qRT-PCR." (PMID 36366842, 2023). "Consistently, our data suggest that ACSL1 gene expression is upregulated by G0S2 ectopic expression in CML, and therefore may play a role in its tumour suppressor activity during CML disease progression and TKI response." (PMID 36536477, 2022). "We hypothesised that G0S2 plays a tumour suppressor role in CML, and that downregulation of G0S2 contributes to reduced responses to TKI therapy." (PMID 36536477, 2022). "Although G0S2 has the properties of a tumor suppressor, it has never been determined if ATGL inhibition is required for G0S2 mediated suppression of cell growth." (PMID 26318046, 2015). "The G0S2 gene has the general properties of a tumour suppressor and has been shown to be a potent negative regulator of triglyceride catabolism." (PMID 26318046, 2015). "Moreover, G0S2 and GPRC5A have been reported to possess tumor suppressive or apoptosis-inducing effects." (PMID 23587162, 2013).
cancer (30 papers, 2010 to 2026). A tumor composed of atypical neoplastic, often pleomorphic cells that invade other tissues. "We also explored the expression of the underlying cancer‐promoting genes within cluster 3; these genes included Cdkn1a, Plaur, Ptgs2, Cox17, Lilrb4q, G0s2, Egr1, and Cxcl2, with previous reports suggesting their implication in increasing cancer progression." (PMID 39113226, 2024). "Since ATGL is the first step in TG catabolism, it is tempting to speculate that observed increases in MAGL activity may be due to loss of G0S2 in cancer cells, leading to enhanced ATGL activity by generating substrates for MAGL." (PMID 26318046, 2015). "G0S2 (3.37-fold increase), which encodes a mitochondrial protein that specifically interacts with Bcl-2, is a proapoptotic factor, and its ectopic expression induces apoptosis in diverse human cancer cell lines in which endogenous G0S2 is normally epigenetically silenced." (PMID 24161199, 2013). "Conversely, the six downregulated genes (SERPINE1, TNFRSF12A, PHLDA1, RNASEK, PPIA, and G0S2) are involved in diverse cancer-related pathways." (PMID 40340807, 2025). "The G0/G1 switch gene 2 (G0S2) has critical functions in cell survival and metastasis of cancer cells and in mediating a pro-inflammatory process by circulating monocytes." (PMID 40340807, 2025). "The G0S2 promoter is methylated and silenced in multiple different cancers, including the K562 CML cell line." (PMID 36536477, 2022). "G0S2 function traditionally relies on protein–protein interactions, such as BCL‐2,13 ATGL17, 67 or nucleolin, and G0S2‐mediated ATGL inhibition was shown to attenuate the growth of cancer cells." (PMID 36536477, 2022). "In cancer cells, G0S2 can similarly regulate LDs lipolysis and promote LDs accumulation in cancer cells by inhibiting ATGL activity." (PMID 35912266, 2022). "From the top down- and up-regulated DEG, four genes (ADAMTS1, FGF1, G0S2 and TP63) were also closely associated with cancer pathways according to the literature." (PMID 35840561, 2022). "NSCL cells were selected as a model since the G0S2 gene was shown to be methylated and silenced in this cancer type and re-expression of the gene was shown to induce death." (PMID 26318046, 2015). "Secondly, it is necessary to validate whether G0S2 exhibits similar functions and its generalizability in immunosuppression across different cancer types." (PMID 40282408, 2025). "Notably, one of these clusters exhibited a significant expression of cancer‐promoting genes, encompassing Cdkn1a, Plaur, Ptgs2, Cox17, Lilrb4q, G0s2, Egr1, and Cxcl2." (PMID 39113226, 2024). "The differences between our results and some of earlier studies of G0S2 in other cancers could reflect context-dependent mechanisms of action in different type of cancers." (PMID 30953555, 2019). "In other cancers, G0S2 is correlated with cancer invasion, apotosis, and metabolism." (PMID 30388142, 2018). "Conversely, knockdown of endogenous G0S2 enhanced the growth and invasiveness of cancer cells." (PMID 26318046, 2015). "First, the G0S2 gene has a potent CpG island in the promoter region and work from several groups have demonstrated that the gene is silenced in many types of human cancer including head and neck cancer, glioma lung and breast cancer." (PMID 26318046, 2015). "By contrast, we observe significant G0S2 hypomethylation and induction in breast, liver and prostate invasive cancer cell lines that suggests the opposite role for this protein in these three cancer types." (PMID 26427334, 2015). "The G0/G1 switch gene 2 (G0S2) is methylated and silenced in a wide range of human cancers." (PMID 26318046, 2015).
cancer (continued). "Moreover, ectopic expression of G0S2 was shown to induce apoptosis in diverse human cancer cell lines in which endogenous G0S2 was normally epigenetically silenced." (PMID 23741337, 2013). "However, it is unknown whether the expression of G0S2 in cancer cells has been involved in H3K27me3 up to now." (PMID 39707168, 2024). "Additionally, G0S2 and SLC25A37 were identified as risk factors for multiple types of cancer." (PMID 37408763, 2023). "G0S2 promotes apoptosis by interacting with the anti-apoptotic protein Bcl-2, and downregulation of G0S2 expression could be a prime avenue for growing cells, especially cancer cells, in preventing death or growth arrest." (PMID 31888477, 2019). "To provide a proof of principle that the list of genes that are commonly hypomethylated and induced in 3 invasive cancer cell lines could serve as a source for discovery of new genes involved in invasiveness, we picked four genes, C11orf68, G0S2, SHISA2 and TMEM156." (PMID 26427334, 2015). "Our research lays the groundwork for exploring G0S2 as a new immunotherapy target, opening new avenues for immunotherapeutic strategies in HCC and other cancers." (PMID 40282408, 2025). "XAF1, TRIM31, G0S2 and IFI6 have known roles in apoptosis or its prevention, while PAX7, TRIM31 and PNMA8A are involved in cell development/development of cancer." (PMID 38990812, 2024). "ACSL3, AIFM2, HSD17B7, LPCAT1, LSS, PLIN3 and RAB10 were up-regulated with the progression of cancer stage of HCC patients, while CIDEB, G0S2, HSD17B13, PLIN1 and PLIN2 were down-regulated." (PMID 37464334, 2023). "As a direct inhibitor of ATGL, the high expression of G0S2 makes ATGL functionally inactivated in cancer cells, ultimately leading to the accumulation of triglycerides and LDs in cancer cells." (PMID 35912266, 2022). "Additional pathways regulated by G0S2 in K562 cells included autophagy, glycosylphosphatidylinositol (GPI)‐anchor biosynthesis, ferroptosis and choline metabolism in cancer." (PMID 36536477, 2022). "However, the function of G0S2 in cancers is still largely unknown." (PMID 30953555, 2019). "Since G0S2 acts as an endogenous inhibitor of ATGL activity, it is possible that elevated ATGL activity is a general property of cancer cells and thus represents an attractive target for therapeutic intervention." (PMID 26318046, 2015). "We selected the genes G0S2, CDKN1A and MYC as master examples for demonstrating the complex role of 1,25(OH)2D3 in the control of cellular proliferation in this cancer cell model." (PMID 24202443, 2013). "A further study ruled out that G0S2 is involved in various biological and pathological processes such as glycolipid metabolism, inflammation, immunization, and cancer." (PMID 37033250, 2023). "It is well known that G0S2 binds to and inhibits adipose triglyceride lipase (ATGL), the rate‐limiting enzyme for intracellular lipolysis, and G0S2‐mediated ATGL inhibition was reported to attenuate the growth of cancer cells." (PMID 36536477, 2022). "Pathway enrichment analysis of our K562 lipidomics data demonstrated that the lipid pathways affected most by differential G0S2 expression included glycerophospholipid metabolism, autophagy, GPI‐anchor biosynthesis, ferroptosis and choline metabolism in cancer." (PMID 36536477, 2022). "However, ATGL regulates lipid metabolism in cancer cells in other pathways outlined in this review, namely, the HIF-1/HIG-2/ATGL axis, PPAR (PPAR-α and PPAR-γ)/G0S2/ATGL axis, and FSP-27/EGR-1/ATGL axis." (PMID 35912266, 2022). "However, one study found that when G0S2 was knocked down in MDA-MB-231 cells, the proliferation, metastasis, and invasive ability of cancer cells were reduced." (PMID 35912266, 2022). "G0s2, the endogenous inhibitor of ATGL, is epigenetically silenced in several types of cancer." (PMID 28459858, 2017).
cancer (continued). "Since G0S2 expression is reduced in such a wide range of cancer cell types, this implies that elevated ATGL activity may be a common property of cancer cells and may represent a novel target for cancer therapy." (PMID 26318046, 2015). "Although the G0S2 gene is silenced in cancer, the impact of ATGL in the growth and survival of cancer cells has never been addressed." (PMID 26318046, 2015).
infection (3 papers, 2013 to 2015). The state of being infected such as from the introduction of a foreign agent such as serum, vaccine, antigenic substance or organism. "We found that overexpression of G0S2 in the liver significantly improved glucose tolerance (P < 0.05 at 30 and 60 min) at days 4 and 8 post-infection." (PMID 23951308, 2013). "Downregulation of G0S2 in SUDHL1 cells resulted in growth retardation of 23% after 5 days of infection when compared to the untreated control cells." (PMID 23741337, 2013). "This hypothesis is in agreement with our preliminary observations indicating that maximal G0S2 expression in the chicken caecum following S. Enteritidis infection is observed 8–12 days after the infection of newly hatched chickens (unpublished data)." (PMID 26046914, 2015). "G0S2 may therefore represent a protein which allows the release of intracellular Salmonella from non-professional phagocytes during recovery from infection and control of respiratory burst by phagocytes, thus decreasing unnecessary damage to the host’s tissues." (PMID 26046914, 2015).
metabolic disorders (3 papers, 2013 to 2020). "In this transcriptome study, the G0/G1 switch gene 2 (G0S2), a candidate gene for metabolic disorders, was upregulated in broilers with FHS." (PMID 31888477, 2019). "Because of this, future investigations could examine a potential role of G0S2 in the well-established link between PTSD and metabolic disorders." (PMID 32171335, 2020).
G0S2 also shares sentences with these, for which no sentence is quoted: lung carcinoma (2 papers); steatosis (2); adrenocortical cancers (1); anaplastic astrocytoma (1); aneurysm (1); atrial fibrillation (1); Cerebral ischemia (1); colorectal cancer (1); coronary artery disease (1); diffuse astrocytoma (1); gestational diabetes (1); hepatoma (1); hyperlipidemia (1); ichthyosis (1); invasive ductal breast carcinoma (1); kidney disease (1); lipid metabolism disorders (1); lipoma (1); melanoma (1); non-alcoholic fatty liver disease (1); prostate carcinoma (1); psoriasis (1); stomach cancer (1); thymoma (1); thyroid cancer (1); triple-negative breast carcinoma (1); type 2 diabetes mellitus (1); Ureteral obstruction (1).